POMC (proopiomelanocortin)
Diseases named in the same sentence as POMC in open-access papers (continued):
Sharing a sentence is not in itself a finding about the gene and the disease.
Hypertension (153 papers, 2007 to 2026). The presence of chronic increased pressure in the systemic arterial system. "Gamma-MSH, for example, has been shown to significantly affect cardiovascular function, high sodium diets increase gamma-MSH and hypertension can be a specific consequence of impaired POMC processing into gamma-MSH." (PMID 39793758, 2025). "POMC neurons have proven to be a key element of leptin-induced sympathetic activation and hypertension development." (PMID 32160920, 2020). "The drug development of MSH agonists has been complicated by a number of side effects, including hypertension, possibly related to the extensive projection of POMC neurons and wide distribution of brain MC-Rs." (PMID 23762342, 2013). "Moreover, selective knockdown of IKK-β in POMC neurons prevented DIO-induced hypertension, whereas IKK-β knockdown in AgRP/NPY neurons was ineffective." (PMID 32160920, 2020).
corticotroph adenomas (107 papers, 2012 to 2026). "In this study the authors report USP48 and BRAF are frequently mutated in USP8 wild-type corticotroph adenomas, and cause Cushing’s disease mainly through promoting the promoter activity of POMC." (PMID 30093687, 2018). "Taken together, the findings indicate that STUB1 is decreased in ACTH-secreting corticotroph adenomas and is negatively correlated with POMC expression and TPIT protein." (PMID 40859326, 2025). "Pasireotide was found to reduce cell proliferation (ranging from 10 to 70%) in primary cultures from six corticotroph adenomas and significantly inhibit proopiomelanocortin transcription and cell proliferation in AtT20 cells." (PMID 39082175, 2025). "The majority of corticotroph adenomas in NS patients produce more proopiomelanocortin transcription products." (PMID 37332454, 2023). "The leftover tumor cells are stimulated to expand until they form a corticotroph adenoma and produce more proopiomelanocortin when CRH is elevated." (PMID 37332454, 2023). "POMC was an important molecule in corticotroph adenomas and were closely related to the secretion of ACTH, so we explored relation between POMC and ubiquitinated proteins." (PMID 35634489, 2022). "From an autopsy pathological study of the human pituitary gland, it has been suggested that SCA originates from pars intermedia POMC-positive cells, while ACTHomas originate from the anterior lobe." (PMID 34220707, 2021). "We present, in a large cohort of corticotroph adenoma, that gene expression of known corticotroph cell markers, POMC, TBX19, and PSCK1 was higher in the functioning group, in accordance with previous reports." (PMID 33066652, 2020). "The finding that glucocorticoids modulate NR3C1, CRH-R1, and POMC gene expression in a different fashion suggests that these effectors play a major role in corticotrope adenomas." (PMID 27220856, 2017). "Additionally, STUB1 was decreased in ACTH-secreting corticotroph adenoma compared to SCAs and negatively correlated with TPIT protein, as well as expression of POMC." (PMID 40859326, 2025). "Furthermore, immunohistochemistry (IHC) showed that nuclear-localized STUB1 was downregulated in ACTH-secreting corticotroph adenomas, accompanied by increased levels of TPIT, POMC, and ACTH compared to SCAs." (PMID 40859326, 2025). "HSP90 is overexpressed in corticotroph adenomas, leading to its continued binding to GR, consequent decreased sensitivity of GR to circulating GC (and dexamethasone, for example), and ultimately increased transcription of POMC." (PMID 29765354, 2018). "In summary, our study identified frequent BRAF and USP48 mutations in corticotroph adenomas carrying wild-type USP8 and indicated that these mutations cause Cushing’s disease mainly by activating POMC gene transcription and increasing plasma ACTH levels." (PMID 30093687, 2018). "Moreover, the higher mRNA abundance of POMC in AtT-20 cells stably transfected with USP48 M415I/V, further supports the notion that the M415I/V substitution causes corticotroph adenomas by up-regulating POMC transcription." (PMID 30093687, 2018). "However, some corticotroph carcinomas develop from “silent” corticotroph adenomas which secrete precursors of ACTH from the prohormone proopiomelanocortin (POMC) detected in ACTH immunoassays." (PMID 24455332, 2013). "Furthermore, PPARγ ligands have demonstrated antiproliferative and apoptotic effects in a murine cell model of corticotropic adenoma cells, and inhibited proopiomelanocortin (POMC) transcription." (PMID 22674211, 2012). "Corticotroph adenoma is characterized by expression of the transcription factor TPIT, which promotes the expression of the pro-opiomelanocortin (POMC) and ACTH secretion." (PMID 40859326, 2025). "EGFR is frequently overexpressed in ACTHomas and is essential for the synthesis of proopiomelanocortin (POMC), an ACTH precursor." (PMID 35954322, 2022).
corticotroph adenomas (continued). "Canertinib, which targets multiple ErbB receptors, suppressed POMC mRNA and ACTH secretion in cultured human corticotroph adenomas, with a 70% reduction seen in those with higher ErbB expression." (PMID 34867776, 2021). "Epidermal growth factor receptor (EGFR) is expressed to varying degrees in human pituitary tissue, including corticotroph adenomas, and EGFR regulates POMC transcription and ACTH production." (PMID 30147673, 2018). "In our study, an elevated kinase activity of BRAF V600E compared to wild-type BRAF was observed in corticotroph adenomas just like in other types of tumors, leading to activation of MAPK pathway and transactivation of POMC, which is the precursor of ACTH." (PMID 30093687, 2018). "In AtT20 cells, a murine corticotroph adenoma cell line commonly used as a model for Cushing disease, as well as in PTTG zebrafish models, R-roscovitine treatment significantly suppressed POMC expression both in vitro and in vivo." (PMID 30147673, 2018). "In rat and human corticotroph adenoma cell lines Rosiglitazone decreased tumor cell growth, increased apoptosis, and lowered ACTH secretion by inhibiting mRNA expression of its precursor-protein pro-opiomelanocortin (POMC)." (PMID 25091295, 2014). "However, the 2017 World Health Organization (WHO) classification of PAs redefined a corticotroph adenoma as a PA that expresses ACTH and other proopiomelanocortin (POMC)–derived peptides and arises from adenohypophyseal cells of pituitary-restricted transcription factor (Tpit) lineage." (PMID 33584540, 2020). "Plasma ACTH, corticosterone levels, and tumor size were significantly reduced in AtT20 cells xenografted in mice with R-roscovitine treatment, and POMC mRNA and ACTH levels were dose dependently suppressed in primary cultures derived from human corticotroph adenomas." (PMID 30147673, 2018).
Hypoglycemia (105 papers, 2007 to 2026). A decreased concentration of glucose in the blood. "Stimulation of epinephrine and glucagon release in response to hypoglycemia or glucopenia was diminished in both POMC- and MC4R-deficient mice, relative to their littermate controls." (PMID 30503832, 2019). "Nevertheless, the POMC-Melanocortin 4 Receptor (MC4R) circuit is essential for the body’s ability to counteract hypoglycemia, as demonstrated by studies showing that POMC or MC4R deficiency impairs glucagon secretion and hepatic glucose production in diabetic mice." (PMID 41409607, 2025). "To test the hypothesis, we induced hypoglycemia or glucopenia in separate cohorts of mice deficient in either POMC or MC4R in the arcuate nucleus (ARC) or the paraventricular nucleus of the hypothalamus (PVH), respectively, and measured their circulating counterregulatory hormones." (PMID 30503832, 2019). "Moreover, humans with POMC mutations have been reported to exhibit hypoglycemia." (PMID 30503832, 2019). "In this case, one can expect that hypoglycemia-mediated excitation of ARC POMC neurons will release melanocortins in the DMV that is an important downstream target of ARC POMC neurons." (PMID 33293550, 2020). "In the context of these findings, we have demonstrated the significance of hypothalamic POMC alone in hypoglycemia counterregulation including stimulation of the release of epinephrine and glucagon." (PMID 30503832, 2019). "We employed FISH using RNAScope reagents to determine if hypoglycemia or glucopenia activate POMC and MC4R neurons in ARC and PVH, respectively." (PMID 30503832, 2019). "The hepatic expression of the gluconeogenic genes Pck1 and G6pc expression was elevated in overnight fasted POMC-TC mice, probably as a compensatory mechanism to prevent hypoglycemia." (PMID 30230471, 2018). "Thus, it is possible that ARC POMC neuron-mediated activation of sympathetic outflow as well as inhibition of parasympathetic cholinergic output would synergistically counteract hypoglycemia." (PMID 33293550, 2020). "•Hypothalamic POMC as well as MC4R is necessary to counteract hypoglycemia." (PMID 30503832, 2019). "Furthermore, release of both of the counterregulatory hormones at 30 min was blunted in ArcPomc−/− mice, indicating the contribution of hypothalamic POMC in counteracting hypoglycemia." (PMID 30503832, 2019). "Interestingly, insulin-induced hypoglycemia increases ARC POMC neuron activity." (PMID 33293550, 2020). "Yet, the necessity of hypothalamic POMC or MC4R in hypoglycemia counterregulation is unknown." (PMID 30503832, 2019). "TCPTP-deficiency in POMC-TC mice increased c-Fos staining (a surrogate marker of neuronal activation) in the PVH of fasted mice and this was exacerbated by insulin; although systemic insulin administration resulted in hypoglycemia, this was similar in Ptpn2fl/fl and POMC-TC mice." (PMID 30230471, 2018). "As insulin-induced hypoglycemia elevated ARC POMC neuronal activity, this ARCPOMC → DMVACh → liver circuit that we identified would plays a critical role in the counterregulatory response to hypoglycemia." (PMID 33293550, 2020). "Using FISH to detect cfos mRNA, we demonstrated that POMC and MC4R neurons in the ARC and PVH, respectively, were activated following hypoglycemia." (PMID 30503832, 2019). "We report that POMC in the ARC and MC4R in the PVH are indispensable to counteract hypoglycemia or glucopenia." (PMID 30503832, 2019). "The expression of c-fos was significantly higher in POMC and MC4R neurons in mice after insulin or 2-DG treatment compared to those injected with PBS, indicating that the neurons were activated following hypoglycemia or glucopenia." (PMID 30503832, 2019). "In addition, insulin-induced hypoglycemia increases ARC POMC neuron activity, supporting the interpretation that ARC POMC neurons may play a critical role in the counterregulatory response to hypoglycemia." (PMID 33293550, 2020).
Hypoglycemia (continued). "Hypoglycemia increases food intake and recent reports show that non-AGRP, non-POMC ARC neurons play a role in feeding." (PMID 33148883, 2020). "Our data demonstrate that GHRH neurons are GABAergic, non-AGRP, non-POMC ARC neurons and activated by hypoglycemia and so could contribute to feeding response." (PMID 33148883, 2020).
diabetes (92 papers, 2009 to 2026). "In vivo correction of this deficit is able to rescue diabetes-induced hyperalgesia and associated behavioral changes, thereby showing the relevance of the dysfunctional POMC-MOR signaling to the increased pain sensitivity observed in diabetes." (PMID 33462216, 2021). "We demonstrate that the underlying metabolic disturbances also cause the malfunction of the antinociceptive POMC-pathway, which constitutes the ‘loss-of-function’, and thereby promote a neuropathic pain state in diabetes." (PMID 33462216, 2021). "Having observed a diabetes-associated downregulation of the endogenous POMC-MOR, it was necessary to establish whether restoration of this axis could be a therapeutic strategy for DPN." (PMID 33462216, 2021). "Conversely, leptin-deficient states (including fasting as well as most forms of diabetes) are characterized by hyperactive AgRP neurons while POMC neurons are inhibited." (PMID 40371641, 2025). "Individuals with POMC and LEPR deficiency experience comorbidities, including diabetes mellitus, frequent infections, and hormonal insufficiencies, which alone can impair QOL." (PMID 35123544, 2022). "Altogether, these data suggest that POMC-specific PERK deficiency in male mice confers protection against DIO, possibly providing a new therapeutic target for the treatment of diabetes and metabolic syndrome." (PMID 34549728, 2021). "We next addressed the regulation of POMC in diabetes by comparing its expression levels in streptozotocin (STZ)-induced diabetic mice and age-matched control mice (STZ-untreated)." (PMID 33462216, 2021). "Here, we report that the sensory neurons of the PNS express POMC in mice and humans and further demonstrate that the endogenous opioid pathway mediated by POMC is impaired during experimental and clinical diabetes." (PMID 33462216, 2021). "We noted that during diabetes, the POMC-MOR opioid pathway was dysfunctional at the level of ligand as well as the receptor." (PMID 33462216, 2021). "In the context of the POMC-pathway in diabetes, sensory ganglia are central to DPN, as are the metabolic changes occurring in them." (PMID 33462216, 2021). "Collectively, it is suggested that NPY/AgRP neurons are more susceptible to l-lactate than the POMC neurons in the hypothalamic ARC, conditions that can be associated with diabetes-induced alterations in feeding behavior." (PMID 33219201, 2020). "Fasting rodents with reduced leptin levels and ob/ob mice exhibit decreased level of hypothalamic POMC mRNA, which is normalized by exogenous leptin administration that subsequently improves obesity and diabetes." (PMID 23579596, 2013). "Here, we report dysfunctional POMC-mediated antinociception in sensory neurons in diabetes." (PMID 33462216, 2021). "Since POMC reactivation completely reverses the diabetogenic phenotype, arcuate POMC could be a potential target for diabetes therapy." (PMID 30283405, 2018). "However, glucose tolerance is completely normalized in arcPomc−/−:Cre after POMC restoration, which further suggests a protective role of POMC against diabetes." (PMID 30283405, 2018). "However, whilst POMC may participate to resolve acute pain under normal physiological conditions, this pathway is impaired during chronic condition such as diabetes." (PMID 33462216, 2021). "This study further points to the occurrence of molecular alterations occurring specifically in the sensory ganglia, which are responsible for downregulation of POMC and MOR in diabetes." (PMID 33462216, 2021). "After observing the efficacy of restoring POMC and MOR against evoked hyperalgesia during diabetes, we further investigated their role in other pain-related non-reflexive behavior by performing gait analysis." (PMID 33462216, 2021). "Our data demonstrate again that sensory ganglia are the seat of changes affecting the POMC-MOR axis, by showing an increased PKC activation and concomitant increase in MOR phosphorylation in the DRG during diabetes." (PMID 33462216, 2021).
diabetes (continued). "Taken together, these findings show that restoring POMC and MOR in the peripheral sensory neurons emerge as a common effective therapeutic strategy against evoked (mechanical and heat) as well as spontaneous neuropathic hypersensitivity during diabetes." (PMID 33462216, 2021). "Although we observed a significant increase in POMC in the pituitary of diabetic mice before and after stroke, the plasma ACTH levels were not significantly altered by stroke and diabetes." (PMID 35784349, 2022). "Both POMC and MOR were remarkably decreased by a magnitude of 50% in ß-tubulin III+ nerves of diabetic patients, irrespective of the type of diabetes or gender compared to non-diabetic subjects." (PMID 33462216, 2021). "Furthermore, this confirmed that downregulation of POMC and MOR during diabetes was not gender-specific." (PMID 33462216, 2021). "Interestingly, icv leptin administration also normalizes excessive glucagon secretion and HPA axis activity in uncontrolled diabetes, whereas icv FGF1 injection does not — and yet, both appear to inhibit AgRP neurons, activate POMC neurons, and thereby increase net melanocortin signaling." (PMID 40371641, 2025).